BCL2 (BCL2 apoptosis regulator)
Diseases named in the same sentence as BCL2 in open-access papers (continued):
Sharing a sentence is not in itself a finding about the gene and the disease.
chondrosarcoma (26 papers, 2003 to 2025). A malignant cartilaginous matrix-producing mesenchymal neoplasm arising from the bone and soft tissue. "In summary, miR-342-5p seems able to limit the expression of Bcl-2 and Bcl-xL, and miR-491-5p seems to be a negative regulator of Bcl-xL, effects that underlie their pro-apoptotic activity in chondrosarcoma cells." (PMID 34070455, 2021). "This can be caused by the high Bcl-xl expression observed in all chondrosarcoma cell lines, which has been reported previously as a possible cause of resistance to selective Bcl-2 inhibition." (PMID 30242253, 2018). "Furthermore, the ACDB-induced chondrosarcoma apoptosis was associated with the upregulation of the B cell lymphoma-2 (Bcl-2) family members including pro- and anti-apoptotic proteins, downregulation of dysfunctional mitochondria that released cytochrome C, and subsequent activation of caspases-3." (PMID 27835579, 2016). "To further validate the effect of miR-6839-5p on apoptosis, we examined the expression of Bcl-2, Bax, cleaved caspase-3, and cleaved caspase-9 apoptotic proteins in chondrosarcoma cells by Western blotting assay." (PMID 38762695, 2024). "Studies conducted on three chondrosarcoma cell lines showed that miR-342-5p has a strong ability to suppress chondrosarcoma by affecting the expression of Bcl-2 and Bcl-xL proteins and inducing apoptosis or autophagy." (PMID 38542153, 2024). "Next, miR-6839-5p downregulated Bcl-2 expression and induce apoptosis in human chondrosarcoma cells." (PMID 38762695, 2024). "Meanwhile, miR-6839-5p significantly down-regulated apoptosis facilitator Bcl-2 expression, and promoted apoptosis of chondrosarcoma cells." (PMID 38762695, 2024). "In chondrosarcoma, negative regulators of the intrinsic or mitochondrial apoptotic pathway such as BCL2, which has crosstalk with SRC, are upregulated and mediate chemo-resistance in cancer." (PMID 34938658, 2021). "In the present study, using functional high-throughput miRNA screening and miRNA target prediction, we selected five miRNAs that can induce apoptosis in the SW1353 chondrosarcoma cell line by targeting BCL2, BCL2L1 or MCL1 mRNAs." (PMID 34070455, 2021). "We identified Bcl-xL and Bcl-2 as direct targets of miR-342-5p, and Bcl-xL as a direct target of miR-491-5p in chondrosarcoma chondrocytes." (PMID 34070455, 2021). "Among these, we identified five miRNAs with putative pro-apoptotic activity because they potentially target anti-apoptotic proteins such as Bcl-xL and Bcl-2, which are thought to play a critical role in the chemoresistance of chondrosarcoma chondrocytes." (PMID 34070455, 2021). "Western blots and luciferase reporter assays identified for the first time Bcl-2 as a direct target of miR-342-5p, and also Bcl-xL as a direct target of both miR-342-5p and miR-491-5p in chondrosarcoma cells." (PMID 34070455, 2021). "The multifunctional tyrosine kinase inhibitor Dasatinib (BMS-354825), which inhibits SRC and down-regulates BCL2 was studied in chondrosarcoma cell lines." (PMID 34938658, 2021). "Protein expression of Bcl-2, Bcl-xl and Bcl-w was determined in a panel of 137 conventional chondrosarcomas." (PMID 30242253, 2018). "Bcl-2 and especially Bcl-xl were highly expressed in chondrosarcoma tissue samples, which correlated with an increased histological grade." (PMID 30242253, 2018). "Taken together, Bcl-xl shows the highest expression in chondrosarcoma, followed by Bcl-2, suggesting that these two Bcl-2 family members are the most important, and were therefore selected for further functional validation." (PMID 30242253, 2018). "Expression of Bcl-2 was variable and found in 100 out of 110 chondrosarcomas (27 were lost from the TMA) and correlated with histological grade in central as well as peripheral chondrosarcoma." (PMID 30242253, 2018).
chondrosarcoma (continued). "Protein expression analysis of apoptotic family members Bcl-2, Bcl-xl, Bcl-w, Mcl-1, Bak and Bax revealed that Bcl-xl was highly expressed in all nine chondrosarcoma cell lines, while Bcl-2 expression was variable." (PMID 30242253, 2018). "We evaluated the expression of the Bcl-2 family members Bcl-2, Bcl-xl and Bcl-w using immunohistochemistry on tissue microarrays containing 137 conventional chondrosarcomas." (PMID 30242253, 2018). "Phosphorylated PI3K/AKT can promote cell growth and decrease apoptosis via increased Bcl-2/BAX ratio in human chondrosarcoma (CS)." (PMID 28887597, 2017). "Once mitochondrial dysfunction occurred, ACDB increased protein levels of Bak (12.9 fold), Bid (4.23 fold) and Bax (1.92 fold) and decrease Bcl-XL (0.24 fold) and Bcl-2 (0.45 fold) protein expression in response to chondrosarcoma cell apoptosis." (PMID 27835579, 2016). "We observed a decrease in expression of Bcl-2 and Bcl-xL, as well as an increase in expression of Bax and Bak, in chondrosarcoma cells after treatment BL-038." (PMID 27618007, 2016). "BPB induced upregulation of Bax, Bad and Bak, downregulation of Bcl-2, Bid and Bcl-XL and dysfunction of mitochondria in chondrosarcoma." (PMID 23211670, 2012). "It has already been reported that chondrosarcoma cells highly express P-glycoprotein and antiapoptotic proteins (Bcl-2, Bcl-xL, XIAP)." (PMID 19445670, 2009). "Based on these data, chondrosarcoma cells were treated with 10 μM of Bcl-2 inhibitor, 10 μM of C-4 (P-glycoprotein inhibitor) or 10 μM of embelin (XIAP inhibitor) and two different concentrations of doxorubicin (0.1 μM and 1 μM)." (PMID 19445670, 2009). "We confirmed that both chondrosarcoma cell types expressed P-glycoprotein and antiapoptotic proteins (Bcl-2, Bcl-xL and XIAP)." (PMID 19445670, 2009). "To confirm P-glycoprotein and antiapoptotic protein expression as a possible mechanism of chemoresistance in chondrosarcoma, we measured P-glycoprotein, Bcl-2, Bcl-xL and XIAP expression by immunoblotting." (PMID 19445670, 2009). "In addition, TOMM20 downregulation using CRISPR‐Cas9 reduced all known BCL2 apoptosis inhibitory proteins in chondrosarcoma (CH2879) and fibrosarcoma (MCA205)." (PMID 39996379, 2025). "It is reasonable to speculate miR-6839-5p might downregulate Bcl-2 expression to induce apoptosis in SW1353 human chondrosarcoma cells." (PMID 38762695, 2024). "Due to the resistance of chondrosarcomas to conventional chemotherapy and radiotherapy, the IDH1/2 mutations could represent a viable option for Bcl-2 inhibitors." (PMID 37720343, 2023). "However, to the best of our knowledge, no study has explored the effect of miRNAs that directly target anti-apoptotic molecules such as B-cell lymphoma-2 (Bcl-2), Bcl-2 lymphoma-extra large (Bcl-xL) and Myeloid cell leukemia-1 (McL-1) in chondrosarcomas." (PMID 34070455, 2021). "In addition Bcl-2 and Bcl-xl inhibition was investigated in an orthotopic Swarm Rat Chondrosarcoma (SRC) model." (PMID 30242253, 2018). "In the majority of the high grade chondrosarcomas high Bcl-2 and Bcl-xl expression is observed, which might suggest that selective Bcl-2 inhibition could be problematic due to high Bcl-xl expression or vice versa." (PMID 30242253, 2018). "In addition a positive correlation between Bcl-2 and Bcl-xl expression was observed, especially in high grade chondrosarcomas." (PMID 30242253, 2018). "Archival material from three extraskeletal myxoid chondrosarcomas, five chordomas, five chondromyxoid fibromas, five chondroblastomas and 25 chondrosarcomas was stained with antibodies against osteonectin, bcl-2, cox-2, actin, calponin, D2-40 (podoplanin), mdm-2, CD117 (c-kit) and YKL-40." (PMID 19594492, 2009).
chondrosarcoma (continued). "Therefore, it is reasonable to speculate miR-6839-5p might downregulate Bcl-2 expression to induce apoptosis in SW1353 human chondrosarcoma cells through the endogenous pathway." (PMID 38762695, 2024). "However, both SOX9 knockdown and knockout cells exhibit a strong increase in apoptosis, accompanied by a reduction of the anti-apoptosis mediator BCL-2 suggesting a potential direct connection between SOX9 and BCL-2 during chondrosarcoma progression to a dedifferentiated stage." (PMID 33076370, 2020). "Bcl-2 was significantly higher expressed in grade II (P = 0.0022) and grade III (P = 0.0002) central chondrosarcoma compared to ACTs." (PMID 30242253, 2018). "Although the role of antiapoptotic proteins in the chemoresistance of chondrosarcoma is not well understood, the overexpression of antiapoptotic proteins (Bcl-2, Bcl-xL, XIAP) is one of the mechanisms of radiation resistance in chondrosarcoma cells." (PMID 19445670, 2009). "siRNA knockdown as well as pharmacologic inhibitors of cell survival proteins (Bcl-2, Bcl-xL and XIAP) enhanced apoptosis of chemoresistant chondrosarcoma cells by up to 5.5 fold at 0.1 μmol and 5.5 fold at 1 μmol doxorubicin." (PMID 19445670, 2009). "Thus, we showed that miR-342-5p directly post-transcriptionally inhibits the anti-apoptotic BCL2 and BCL2L1 mRNAs and that miR-491-5p directly post-transcriptionally inhibits BCL2L1 mRNA in SW1353 chondrosarcoma cells." (PMID 35337159, 2022). "Although we validated BCL2 mRNA as a direct target of miR-342-5p in our previous study on chondrosarcomas, here, we did not validate BCL2 mRNA as a real direct target of miR-342-5p." (PMID 35337159, 2022). "MiR-491-5p did not influence the expression of the Bcl-2 anti-apoptotic protein in any of the three investigated chondrosarcoma cell lines sensitive to miR-491-5p." (PMID 34070455, 2021). "In contrast, in our study, miR-491-5p, which inhibits Bcl-xL, and miR-342-5p, which downregulates both Bcl-2 and Bcl-xL, did not chemosensitize chondrosarcoma cells to CDDP." (PMID 34070455, 2021). "In the three chondrosarcoma cell lines, miR-342-5p inhibited the expression of the anti-apoptotic proteins Bcl-2 and Bcl-xL, but not that of McL-1, with a more sustained effect under hypoxia." (PMID 34070455, 2021). "Our research group published that the reported synthetic lethal interaction between IDH mutations and Bcl-2, NAMPT, and glutaminase inhibition was absent in chondrosarcoma." (PMID 31810230, 2019). "Additionally, knock down of anti-apoptotic Bcl-2 family members Bcl-2, Bcl-xl and XIAP has been shown to increase cell death after radiation in chondrosarcoma cell lines." (PMID 31160965, 2019). "Selective Bcl-xl inhibition with WEHI-539 was effective at relatively high doses in a subset of chondrosarcoma cell lines, which did not correlate with expression of Bcl-2 or Bcl-xl." (PMID 30242253, 2018). "In contrast, no sensitivity for Bcl-2 inhibition using S55746 was observed in any of the chondrosarcoma cell lines tested, while the positive control cell line HL-60 showed a dose dependent decrease in viability." (PMID 30242253, 2018). "In addition, the ratio of Bax protein to both Bcl-2 and caspase-cleaved PARP – key executors of cell apoptosis – increased in chondrosarcoma cells transfected with siHOT, as analyzed by western blot." (PMID 28182000, 2017). "The author compares peripheral chondrosarcomas with secondary peripheral chondrosarcomas and notes the lack of CD44v3 and lower BCL-2 expression." (PMID 28439237, 2017). "Yet, the knockdown of Bcl-2 did not induce significant apoptosis in SW1353 chondrosarcoma cells while Bcl-2 inhibitor treatment enhanced doxorubicin sensitivity in SW1353 cells." (PMID 19445670, 2009).
chondrosarcoma (continued). "Conversely, selective inhibition of Bcl-2 was not effective in chondrosarcoma cell lines and could not sensitize to chemotherapy." (PMID 30242253, 2018). "Inhibition of Bcl-xl with WEHI-539 led to increased sensitivity to doxorubicin or cisplatin treatment in a subset of chondrosarcoma cell lines, while combination treatment with Bcl-2 inhibitor S55746 and chemotherapy did not result in a difference in sensitivity compared to single treatment." (PMID 30242253, 2018). "However, while the cell lines show a heterogeneous response with respect to chemo-sensitization, with a preference for chemo-resistant cell lines with high Bcl-xl and low Bcl-2 and Bcl-w expression, the SRC model represents only a subset of the chondrosarcomas." (PMID 30242253, 2018). "Although half of the chondrosarcoma cell lines showed Bcl-2 expression, none of the cell lines was sensitive for selective Bcl-2 inhibition with S55746 and only one cell line (CH2879) showed a small increase in sensitivity for doxorubicin when treated in combination with the Bcl-2 inhibitor." (PMID 30242253, 2018). "All 25 chondrosarcomas showed a positive staining reaction for D2-40, none for actin and CD117, and a partial reactivity for bcl-2 (36%)." (PMID 19594492, 2009).
diabetic nephropathy (26 papers, 2014 to 2026). "In podocytes exposed to high glucose, a model for diabetic kidney disease, UA improved cell survival and decreased apoptosis through the Bcl-2/caspase-3 pathway and by increasing autophagy markers." (PMID 41374004, 2025). "In diabetic nephropathy, factors such as high blood glucose disrupt the balance between Bax and Bcl-2, leading to a relative increase in Bax and a relative decrease in Bcl-2." (PMID 41394140, 2025). "It should be noted that increasing β-catenin expression in diabetes nephropathy can trigger mitochondrial-mediated apoptosis in podocytes by Bax/Bcl-2/caspase-3 pathway." (PMID 40417210, 2025). "Wogonin can directly bind to BCL2 and regulate the autophagy and apoptosis of glomerular podocytes, thereby alleviating diabetic nephropathy." (PMID 39730319, 2024). "In the same context, evident anti-apoptotic effects of linagliptin have been described in a diabetic nephropathy model in db/db mice through dampening caspase 3 activity and upregulation of the anti-apoptotic Bcl2." (PMID 35890148, 2022). "In conclusion, our work shows that the dual inhibition therapy with LCZ696 had protective benefits against HFD/STZ-induced diabetic nephropathy by reducing oxidative stress and inflammation by regulating NF-κB and Bax/Bcl-2/caspase-3 signaling pathways." (PMID 36359384, 2022). "Other studies have also demonstrated that during diabetic nephropathy, the expression of Bcl-2 decreased and expressions of Bid and Bax increased." (PMID 28610566, 2017). "Besides, increasing β-catenin expression in diabetes nephropathy can trigger mitochondrial-mediated apoptosis in podocytes by Bax/Bcl-2/caspase-3 pathway." (PMID 40417210, 2025). "Similarly, studies have confirmed that kidney biopsies from patients with diabetic nephropathy show significantly reduced BCL2 expression." (PMID 39730319, 2024). "In the same study decreased levels of BCL-2 were described in patients with diabetic nephropathy." (PMID 36429063, 2022). "Importantly, we found that Bcl-2 expression levels were decreased in renal tissues of patients with diabetic nephropathy." (PMID 34253875, 2022). "Moreover, the Bcl-2 expression had significantly decreased in the renal tissue of diabetic nephropathy patients." (PMID 36699321, 2022). "Importantly, we found that Bcl-2 expression levels were significantly decreased in renal tissues of diabetic nephropathy patients." (PMID 34253875, 2022). "Interestingly, we found that the expression of Bcl-2 was significantly decreased in biopsy renal tissue of diabetic nephropathy patients." (PMID 34253875, 2022). "However, it can also induce mesangial cell apoptosis by targeting BCL2 under high glucose, predicting kidney injury in diabetic nephropathy." (PMID 34571708, 2021). "This study shows that Spilanthes filicaulis alleviates oxidative stress and the development of diabetic nephropathy via downregulation of the cAMP/PKA/CREB/cFOS signaling pathway and upregulation of the antiapoptotic protein Bcl-2." (PMID 38640098, 2024). "Previous research reported SA possessed anti-apoptotic activity against diabetic nephropathy via suppression of BAX expression and increase of BCL-2 expression." (PMID 35432808, 2021). "We also found that expression level of apoptotic makers was increased under diabetic nephropathy conditions, and PCS extract treatment attenuated cleaved PARP and increased Bcl-2 expression and phosphorylation of Bad (Ser-112)." (PMID 28767064, 2017). "In a diabetic nephropathy model, the administration of mitochondria effectively abolished ROS production by restoring the levels of superoxide dismutase 2 (SOD2) and preventing apoptosis through the upregulation of Bcl-2 protein." (PMID 40741287, 2025).